EGFR (epidermal growth factor receptor)
Diseases named in the same sentence as EGFR in open-access papers (continued):
Sharing a sentence is not in itself a finding about the gene and the disease.
tumor (continued). "Positive expression of EGFR is associated with poor clinical outcome in several tumor types, including TNBC." (PMID 27655662, 2016). "The success of anti-tumor therapy with epidermal growth factor receptor (EGFR) inhibitors for patients harboring activating EGFR mutations is only one example emphasizing the potential for personalized treatment approaches." (PMID 27501455, 2016). "PET using carbon-11-labeled erlotinib, [11C]erlotinib, allowed to visualize and quantify tumor [11C]erlotinib uptake in patients with EGFR-mutated NSCLC." (PMID 26857779, 2016). "Tumor EGFR mutation, KRAS mutation and ALK rearrangement status were available for 124 (72.5 %), 126 (74 %), and 167 (98 %) patients, respectively." (PMID 27422280, 2016). "The tumour of 6 (3.0 %) and 23 (11.4 %) of the 202 explored patients died within 1 and 3 months following diagnosis carried the EGFR mutation." (PMID 27039176, 2016). "Consistently, ZEB1 also promoted KRAS-mutated xenograft tumour growth but suppressed EGFR-mutated xenograft tumour growth." (PMID 27456471, 2016). "As proof of principle, we recovered single cells from CTC samples via WBCs depletion on the device and correlated EGFR mutations to its primary tumor molecular characteristics." (PMID 26924553, 2016). "The tumor sizes of the five patients were all ≤ 3 cm and significantly smaller than those of patients with either EGFR mutations or ALK fusions(P=0.017, P=0.011)." (PMID 27563816, 2016). "In patient #8, RC-seq detected a putative tumour-specific L1 mutation in the first intron of the epidermal growth factor receptor gene (EGFR), a major oncogene amplified or otherwise altered in >60 % of GBM cases." (PMID 27843499, 2016). "In xenograft and transgenic models of NSCLC with EGFR mutations including T790M, rociletinib resulted in durable tumor shrinkage." (PMID 27071706, 2016). "NPC prognosis has been found to be associated with some biomarkers based on individual tumor characteristics: such as Epstein-Barr virus DNA, epidermal growth factor receptor and ERCC1." (PMID 27549330, 2016). "Of note, many studies have indicated that EGFR has a potent effect on tumor-associated angiogenesis and combined treatment with anti-EGFR and anti-VEGF antibodies have at least additive antitumor activity." (PMID 27729020, 2016). "The epidermal growth factor receptor (EGFR) pathway plays a core role in regulating tumor cell growth and survival, and is associated with poor prognosis in GC." (PMID 27014419, 2016). "Seventy-three advanced ADC patients with tumor tissues carrying EGFR mutations and their matched pre- and post-EGFR-TKIs plasma samples were enrolled in this study." (PMID 26989078, 2016). "Overexpression and mutations of epidermal growth factor receptor (EGFR) are associated with tumor cell growth, differentiation, proliferation, apoptosis and cellular invasiveness." (PMID 27602494, 2016). "This has led to the approval of many drugs capable to target specific molecular alterations in a certain tumor, e.g., gefitinib in EGFR-mutated non-small cell lung cancer or trastuzumab in HER2-amplified or overexpressed breast cancer." (PMID 28050231, 2016). "The EGFR signaling pathway is importantly implicated in tumor cell growth, migration, angiogenesis, metabolism and metastasis." (PMID 27057632, 2016). "Several studies have demonstrated heterogeneity of EGFR mutation status in different ‘primary tumor’ fragments." (PMID 27685950, 2016). "While EGFR signalling is critical for the control of many normal cell functions, the aberrant activity of EGFR by mutation and overexpression has played a key role in the origin and development of tumour cells." (PMID 27463710, 2016). "Taking the EGFR mutation in tumor tissue as the golden standard, the concordance of EGFR mutations detected in ctDNA was 74% (54/73)." (PMID 26989078, 2016).
tumor (continued). "The tumor was positive for an epidermal growth factor receptor L858R mutation in exon 21 using the peptide nucleic acid-locked nucleic acid polymerase chain reaction clamp method." (PMID 26724810, 2016). "This study was a pre-planned exploratory analysis of a randomized phase III trial conducted from 2009 to 2014 comparing erlotinib with gefitinib in advanced NSCLC harboring EGFR mutations in tumor (CTONG0901)." (PMID 27619632, 2016). "The prognostic impact of preoperative serum tumor markers should be evaluated together with EGFR mutation status." (PMID 27072585, 2016). "As an example, the clinical prescription of third-generation EGFR TKIs requires the proof of the presence of the T790M resistance mutation in tumor cells." (PMID 26970967, 2016). "Although tumor tissue is the gold standard for detection of EGFR mutation status, major barriers exist in terms of acquisition and utility." (PMID 27081078, 2016). "Exosomal mediated transfer of oncogenic EGFR from human squamous cell carcinoma to tumor-associated endothelial cells was shown to activate MAPK and AKT cell signaling pathways and to promote endothelial VEGF expression." (PMID 26919248, 2016). "At present, when ROS1 testing is required, it will be reasonable to test the same tumours currently being selected for EGFR mutation and ALK gene rearrangement." (PMID 27535289, 2016). "This approach, which has been validated, represents a surrogate DNA source and is a novel strategy for tumor genotyping, mainly applicable at the time of progression for EGFR-mutated patients." (PMID 28149837, 2016). "The relatively lower clinical sensitivity of EGFR mutations in patients at the time of disease progression (65%) is likely attributed to the tumor shrinkage after drug treatment and the collection time of plasma samples near or at the PD stage." (PMID 26755650, 2016). "Sixty percent (12/20) of tumours had EGFR gains (11 gains, 1 amplification), consistent with previous reports; 10 tumours had PTEN loss." (PMID 27923043, 2016). "The concordance of EGFR mutation status between the tumor tissue and plasma was 82 % (95 % confidence interval [CI], 76.5–87.4), and it presented a sensitivity of 66.7 % (95 % CI, 60.0–73.3) and a specificity of 87.4 % (95 % CI, 82.7–92.1)." (PMID 27519791, 2016). "EGFR expression has been reported to be significantly correlated with high tumor grade, advanced stage, high risk for PSA recurrence and shorter progression-free survival." (PMID 27611943, 2016). "Of the 211 AC tumours, 117 (55.5%) featured an EGFR-sensitive mutation (deletion in the exon 19 frame, or L858R), and 67 were EGFR wild typed." (PMID 27046167, 2016). "Different mutations were also observed in STK11 in patient 1 (a missense mutation p.K78N in tumour 1 and a nonsense mutation p.Q37X in tumour 2) and in EGFR in patient 4 (p.L858R in tumour 1 and p.S229C in tumour 2)." (PMID 27767028, 2016). "In approximately half of patients, tumor resistance is associated with the acquisition of a secondary EGFR mutation (Thr790Met modification)." (PMID 27248176, 2016). "Activation of EGFR is implicated in a variety of tumor types, including lung, colon, pancreas, and bladder cancer." (PMID 27248176, 2016). "KRAS mutations are associated with tumor resistance to EGFR TKIs (erlotinib, gefitinib) and to monoclonal antibody against EGFR (cetuximab)." (PMID 25902737, 2016). "EGFR inhibitors are approved for EGFR mutation positive tumours and anaplastic lymphoma kinase inhibitors are approved for EML4-ALK fusion positive tumours." (PMID 26905262, 2016). "In unselected patients, 10-50% of tumour biopsies are EGFR mutation positive with L858R and exon 19 deletions in the tyrosine kinase domain accounting for up to 90% of all mutations." (PMID 27409166, 2016). "This intra-tumor heterogeneity of EGFR mutation can be reflected by the quantification of EGFR mutant alleles in ctDNA detected by ddPCR." (PMID 26989078, 2016).
tumor (continued). "Our study advanced the explanation of the oncogenic effect of the E545K mutation by demonstrating that this mutation promotes tumor progression through enhanced binding to EGFR in GBC." (PMID 27317099, 2016). "Under the strong selective pressure of EGFR-TKIs, the tumor developed secondary T790M and tertiary C797S mutations in the EGFR gene to bypass the TKIs and maintain EGFR signaling." (PMID 27448564, 2016). "Afatinib was found effective in reducing tumor size in transgenic mice with T790M-L858R mutation and other exon 20 insertion EGFR mutations." (PMID 26911310, 2016). "Together, these results demonstrated that the E545K mutation of PIK3CA promotes tumor progression in GBC via enhancement of the binding to EGFR." (PMID 27317099, 2016). "In the case of EGFR mutant tumours, DUSP6/MKP-3 loss appears secondary to down regulation of the transcription factor and ERK signalling target Ets1, while the mechanism of DUSP6/MKP-3 down regulation in ELM4–ALK tumour cells was not studied." (PMID 26791049, 2016). "When primary tumor size was classified in 5 groups (≤2, 2.01–3, 3.01–5, 5.01–7, and >7), there was a trend of lower incidence of EGFR mutations in larger tumors (48.3%, 52.4%, and 40.6%, 14.6%, 18.5%, respectively; P < 0.001)." (PMID 27472739, 2016). "As signaling through EGFR is a major inducer of EMT in epithelial cells, we have investigated the effect of EGFR inhibition with erlotinib on tumor phenotype and susceptibility to immune attack." (PMID 27685624, 2016). "Advanced LADCs with EGFR mutations are often inoperable and are treated with tyrosine kinase inhibitors; however, these tumours frequently become drug resistant, leading to disease progress and death." (PMID 27501781, 2016). "In sum, our study revealed SQCCs in never-smokers to be a distinct subtype that occurs disproportionally in females and is characterized by poor tumor differentiation and relatively high frequency of EGFR mutations along with other known oncogenic mutations." (PMID 27092882, 2016). "Here, we report our clinical data to show that EGFR kinase domain mutation-positive NSCLC is associated with dramatic regression of patient's tumor to IPHC followed by cycles of systemic chemotherapy (IPHC-CT) and longer overall survival." (PMID 26654941, 2016). "Correlations between serum tumor marker levels and EGFR mutations and survival parameters were analyzed and prognostic factors were identified." (PMID 27072585, 2016). "Although non-invasive genetic testing methods exist, mutation detection using tumor tissues is still the gold standard for EGFR mutation testing." (PMID 27738317, 2016). "Although patients carrying these mutations respond favorably to EGFR inhibition, tumor relapse is common within one to two years of treatment due to acquired resistance to therapy." (PMID 27248176, 2016). "All patients presented with stage III or IV disease and carried EGFR mutations as confirmed by molecular pathological analysis of tumor tissue." (PMID 27640882, 2016). "Consistent with this previous finding, we found that the concordance for T790M mutation detection by ddPCR with paired plasma and either tumor tissue or malignant fluid samples obtained after the development of EGFR-TKI resistance was 65.9%." (PMID 27542267, 2016). "EGFR activation has been associated with tumor progression in different types of cancer in humans and mice, including NMSC, and usually correlates with a worse prognosis." (PMID 27121058, 2016). "It has also been implicated as a tumor suppressor found to work with the BRCA protein to downregulate EGFR." (PMID 27323855, 2016). "Twenty-seven rebiopsy samples were analyzed using our tumor genotyping panel, and 34 samples were examined for EGFR mutations by commercial clinical laboratories." (PMID 27821131, 2016). "Vascular endothelial growth factor (VEGF) and epidermal growth factor receptor (EGFR) are considered to have an important role in tumor-associated angiogenesis." (PMID 27729020, 2016).
tumor (continued). "For example, EGFR exon 19 deletions are associated with the tumor susceptibility to EGFR targeted therapy while KRAS mutations are associated with the tumor resistance to EGFR targeted therapy." (PMID 27597976, 2016). "Inhibition of EGFR signaling leads to apoptosis of EGFR mutation positive tumor cells, a phenomenon termed oncogene addiction." (PMID 26654941, 2016). "Our data suggest that impending tumor progression is characterized by a continuous increase of EGFR sensitizing (and, in several cases, resistance) mutations up to four months before clinical symptoms were observed." (PMID 27640882, 2016). "Screening for EGFR gene mutations in histological and/or circulating tumor cell or DNA samples of NSCLC patients can identify patients who would have a response to EGFR-TKIs or acquire resistance during the treatment." (PMID 27866520, 2016). "Afaitnib has shown anti-tumor activity against metastatic EGFR-mutated NSCLC after prior failure to first generation EGFR-TKI and chemotherapy." (PMID 26911310, 2016). "The ctDNA carries the same somatic alterations as the tumor itself and can be used to detect clinically relevant mutations such as those in the epidermal growth factor (EGFR) or KRAS genes." (PMID 28066769, 2016). "Several studies have shown that serum tumor markers were associated with EGFR mutation status and capable of predicting the efficacy of EGFR-TKI therapy in advanced NSCLC." (PMID 27072585, 2016). "The Sanger sequencing method was unable to detect EGFR mutations in two cases, because the mutation rate was below the detection limit of 15% of the whole tumour." (PMID 26923333, 2016). "Several studies have reported a concordance rate between tumor and plasma >90 %, even reaching 97 %, demonstrating the feasibility of detecting EGFR mutations in cfDNA." (PMID 27619632, 2016). "The highest risk of death within 5 years was observed in patients with tumours displaying high expression of both EGFR and PODXL in cohort 1 and 3 (HR 1.97; 95 % CI 1.18–3.28 and HR 3.56; 95 % CI 1.75–7.22, respectively)." (PMID 27160084, 2016). "From January 2006 through March 2010, tumor tissue from 229 phenotypically selected patients was analyzed for the presence of EGFR kinase domain mutations." (PMID 27032107, 2016). "Nevertheless, all patients with a mCRC harboring RAS PLLM and/or RAS mutations in a limited part of the tumor (i.e., intra- or inter-tumoral heterogeneity), and treated with anti-EGFR mAbs showed disease progression (n = 5)." (PMID 27916952, 2016). "As reported by Koga, 16.7 μg/g of free cisplatin was detected in pleural metastatic tissues; and 2) increased cisplatin accumulation in tumor cells under hyperthermic condition as we saw in EGFR mutation positive cell lines." (PMID 26654941, 2016). "We found that the expression of AREG/EGFR co-expression were associated with poor tumor differentiation, which is consistent with previous studies." (PMID 27391842, 2016). "Tumor heterogeneity associated with anti-EGFR resistance poses challenges to targeted therapeutics in CRC." (PMID 27699178, 2016). "There were modest HER2 increases (p = 0.034, 29% tumours) and loss of any detectable EGFR phosphorylation (p = 0.024, 50% tumours) and MAP kinase (ERK1/2) phosphorylation (p = 0.019, 65% tumours) by 6 months." (PMID 26178788, 2016). "In univariate analysis, EGFR mutation status was significantly associated with sex, smoking status, tumor histology, tumor grade, primary tumor size, and SUVmax of the primary tumor." (PMID 27472739, 2016). "A number of studies find that JNK activation is frequently accompanied by activation of Akt and PI3K in tumor cells upon PTEN loss or epidermal growth factor receptor (EGFR) overexpression." (PMID 27176481, 2016). "We found that overexpressing integrin can significantly (Student's t-test, P<0.0001) rescue the GSC tumour phenotypes associated with the loss of EGFR-ERK signalling and overexpression of zfh-1 and hopTum−l." (PMID 26792023, 2016).
tumor (continued). "The concordance between tissue and plasma genotyping for EGFR activating and T790M mutations in pre-treatment tumour biopsies and plasma was 95% (41 of 43) and 91% (39 of 43), respectively." (PMID 27283993, 2016). "The significantly mutated cancer-related genes that were identified in tumor tissue included EGFR, KDR, FGFR2, and RET." (PMID 27149458, 2016). "Currently, tumor tissue, which is usually obtained by biopsy or surgery, is the gold standard for detection of EGFR mutations." (PMID 27081078, 2016). "Bronchoscopic biopsy of the tumour revealed stage IV poorly differentiated adenocarcinoma with epidermal growth factor receptor (EGFR) gene mutation (L858R point mutation)." (PMID 27543609, 2016). "We also found that AREG/EGFR co-expression was associated with poor tumor differentiation, which is similar to that demonstrated in previous studies." (PMID 27391842, 2016). "Due to limited tumor availability, EGFR mutation testing was only possible on 8/24 study patients (all wild-type, including the SCC patient with stable disease)." (PMID 27036206, 2016). "Genetic induction of PTEN expression in combination of with the EGFR inhibitor gefitinib synergistically suppresses PTEN-deficient and EGFR-overexpressing BLBC tumor growth and causes tumor regression." (PMID 27484095, 2016). "We have recently shown in the rat model that invasive tumour growth is strongly associated with EGFR gene amplification and receptor activation." (PMID 27049916, 2016). "Targeting EGFR has already been associated with cell cycle arrest at the G1 phase in several cancer cell lines and human tumor xenografts studies." (PMID 27655662, 2016). "The mRT-PCR test tended to detect more CTCs (42.9%) among patients with an altered EGFR status of the primary tumour, including EGFR mutations, amplifications and high polysomy compared to patients with an EGFR wildtype status (17.4%, p = 0.091)." (PMID 27302574, 2016). "In EGFR-mutated LADCs, the proportion of mPAP element in the tumor at the advanced stage (stage II, III, or IV) was significantly higher than that in the tumor at the early stage (stage I) (Mann-Whitney test, P<0.0001)." (PMID 27861549, 2016). "This translates into more profound tumour responses and longer time to anti-EGFR treatment failure in patients who preferentially develop EGFR ECD mutations." (PMID 27929064, 2016). "The combination treatment led to DNA damage in ER NSCLC cell lines harboring T790M EGFR mutations marked apoptosis in the ER cell lines with T790M mutations, and decreased tumor growth in mice." (PMID 27384992, 2016). "EGFR overexpression or constitutive activation has been associated with increased tumor proliferation, survival, migration, and metastasis." (PMID 27806094, 2016). "Compared with NSCLC tumor tissues, the pooled sensitivity and specificity of cfDNA for the detection of EGFR mutation status were 0.60 (95% confidence intervals (95% CI) = 0.57–0.62) and 0.94 (95% CI = 0.93–0.95), respectively." (PMID 27081078, 2016). "Compared with the wild-type EGFR patients, the EGFR L858R mutation patients demonstrated clear differences in terms of tumor site, pathological stage and type, tobacco use status, tumor size and visceral pleura invasion status." (PMID 26739511, 2016). "The primary end point is PFS, and the secondary end points include assessment of PFS by pretreatment T790M mutation status and by EGFR mutation subtype (exon 19 deletion or L858R) detected in circulating tumor DNA." (PMID 27071706, 2016). "A total of 25 tumour tissues with activating EGFR mutations L858R (n=12) and E19 deletions (n=10) as well as activating ALK fusions (n=3) and matching control tissue were selected for comparative analysis." (PMID 27409166, 2016). "The distribution of fragment lengths of the EGFR WT allele between tumor patients and healthy controls largely reflected differences seen in S5 Fig, although noisier due to fewer total reads." (PMID 27428049, 2016).